NIT2 (nitrilase family member 2)
Description:
Has omega-amidase activity. The role of omega-amidase is to remove potentially toxic intermediates by converting 2-oxoglutaramate and 2-oxosuccinamate to biologically useful 2-oxoglutarate and oxaloacetate, respectively.
Synonyms: HEL-S-8a
Tractability: Antibody: its Gene Ontology location is reachable by antibodies, with high confidence. PROTAC: ubiquitination databases record sites on it; its protein half-life has been measured.
Target class: Enzyme; Hydrolase
Gene: Protein-coding gene on chromosome 3 (100,334,625 to 100,361,635, forward strand). Ensembl gene ENSG00000114021.
Subcellular location: Cytoplasm
Subcellular location (Human Protein Atlas): Cytosol; Centrosome
Pathways (Reactome):
Immune System: Neutrophil degranulation
Gene Ontology:
Molecular function: 2-oxoglutaramate amidase activity; omega-amidase activity; hydrolase activity, acting on carbon-nitrogen (but not peptide) bonds, in linear amides
Biological process: L-methionine salvage; tricarboxylic acid cycle; glutamine metabolic process
Cellular component: cytosol; extracellular exosome; mitochondrion; extracellular region; specific granule lumen; tertiary granule lumen; cytoplasm
Genetic constraint (gnomAD): Loss-of-function variants: 22 observed, 25.16 expected, observed/expected ratio (o/e) 0.87, 90% interval 0.62 to 1.25. The upper end of that interval is the gene's LOEUF score, 1.25, which puts it in group 5 of 6, group 1 being the genes least tolerant of losing a copy. Missense variants: 210 observed, 248.07 expected, observed/expected ratio (o/e) 0.85, 90% interval 0.76 to 0.95. Synonymous variants: 86 observed, 91.21 expected, observed/expected ratio (o/e) 0.94, 90% interval 0.79 to 1.13.
Homologues: Orthologues: chimpanzee NIT2 (99% identical), macaque NIT2 (98% identical), guinea pig NIT2 (92% identical), pig NIT2 (91% identical), rabbit NIT2 (91% identical), mouse Nit2 (89% identical), dog NIT2 (88% identical), rat Nit2 (88% identical), tropical clawed frog nit2 (78% identical), zebrafish nit2 (74% identical), Drosophila melanogaster CG8132 (53% identical). Paralogues in human: NIT1 (38% identical), UPB1 (22% identical).
Diseases named in the same sentence as NIT2 in open-access papers:
NIT2 is named in the same sentence as 8 diseases in open-access papers, as found by Europe PMC text mining. Sharing a sentence is not in itself a finding about the gene and the disease. The quoted sentences say what the papers report.
colon cancer (4 papers, 2016 to 2024). "Moreover, folate deficiency (which is associated with increased risk of colon cancer in humans) in human colonocytes in culture resulted in a remarkable ~98% loss of Nit2 (i.e., ω-amidase) protein, as assessed by staining intensity of the Nit2 protein spot on a 2D gel." (PMID 37627015, 2023). "In colon cancer, the downregulation of NIT2 inhibits the proliferation of colon cancer cells and induces cell cycle arrest through the caspase-3 and PARP pathways." (PMID 39003419, 2024). "A previous study indicated that the down-regulation of NIT2 inhibited the proliferation of colon cancer cells through the caspase-3 and PARP pathways, and induced cell cycle arrest." (PMID 34120619, 2021). "Their data indicated that Nit2, a member of the nitrilase protein family, which also has been reported as a suppressor, acts as an oncogene in human colon cancer." (PMID 26967383, 2016). "Meanwhile, low expression of NIT2 may not only inhibit the growth of colon cancer cells, but also promote apoptosis of cancer cells, indicating that NIT2 may play a role in promoting cancer." (PMID 39003419, 2024).
kidney cancer (1 paper, 2023). Primary or metastatic malignant neoplasm involving the kidney. "The Human Protein Atlas also notes that Nit2 protein can be detected by immunohistochemical staining in a variety of human tumors, with the highest staining intensity in liver and kidney cancers." (PMID 37627015, 2023).
lung carcinoma (1 paper, 2016). "Our data showed that knocking down NIT1, but not NIT2, can decrease cell viability in various lung cancer cell lines, and that it can be rescued after NIT1 expression levels were restored with recombinant human Nit1 adenovirus." (PMID 26967383, 2016).
tumor (5 papers, 2014 to 2024). "nit2 is a member of the nitrilase family which acts as a tumor suppressor in human cells and estX encodes esterase X of unknown function found in integrons." (PMID 25084116, 2014). "We further performed PDUI analysis of CISD2 and NIT2 in 56 paired samples, and the results also showed that the PDUI value of CISD2 and NIT2 were also significantly lower in LUAD tumor tissues (P = 8.80 × 10−17, P = 2.88 × 10−5)." (PMID 39003419, 2024). "The results showed that the tumor volume growth rate in the NIT2-rs277646-G group was slower, while the tumor volume growth rate in the NIT2-rs277646-T group was faster and suddenly increased from the 22nd day." (PMID 39003419, 2024). "The mRNA expression level of CISD2 (P = 2.07 × 10−12) and NIT2 (P = 1.23 × 10−7) were both significantly higher in the LUAD tumor tissues (n = 57) from TCGA database." (PMID 39003419, 2024). "This implies that the 3′UTR length of CISD2 and NIT2 were significantly shorter in LUAD tumor tissues compared with adjacent non-tumor tissues." (PMID 39003419, 2024). "Using TCGA database, the PDUI value of CISD2 and NIT2 were significantly lower in total LUAD tumor tissues compared with adjacent non-tumor tissues (P = 2.01 × 10−55, P = 2.90 × 10−7)." (PMID 39003419, 2024). "The endogenous function of this enzyme remains poorly understood in animal systems, however, there are some indications that NIT2 functions as a tumor suppressor in humans." (PMID 31036678, 2019). "In addition, after killing the mice on the 30th day, the tumor weight of the NIT2-rs277646-T group significantly increased compared to the NIT2-rs277646-G group." (PMID 39003419, 2024). "Resulting in an increase in the expression of NIT2 in LUAD tumor tissues, this in turn may affect protein expression levels, population susceptibility, and disease outcomes." (PMID 39003419, 2024). "Finally, the correlation between PDUI and NIT2 expression in LUAD tumor tissues is moderate, with a |Rs| value of 0.320, slightly exceeding 0.3, suggesting a potential risk of insufficient correlation significance, which may warrant further consideration and validation." (PMID 39003419, 2024). "Nitrilase family member 2 (NIT2) has ω-amidase activity and possesses inhibiting effects on tumor cell growth." (PMID 32602849, 2020). "The result showed that the mRNA expression level of CISD2 and NIT2 were also higher in LUAD tumor tissues (n = 49) compared with paired adjacent non-tumor tissues (P = 4.31 × 10−3, P = 7.38 × 10−6)." (PMID 39003419, 2024). "In addition, the PDUI value of NIT2 was also negatively correlated with NIT2 gene expression level in both adjacent non-tumor tissues (Rs = −0.371, P = 4.12 × 10−3), LUAD tumor tissues (Rs = −0.320, P = 5.60 × 10−13), and total tissues (Rs = -0.361, P = 3.82 × 10−18)." (PMID 39003419, 2024).
cancer (4 papers, 2023 to 2025). A tumor composed of atypical neoplastic, often pleomorphic cells that invade other tissues. "Thus, the role of Nit2/ω-amidase in promoting or suppressing cancer is controversial and needs to be further investigated, as does the possible role of Nit2/ω-amidase phosphorylation in these processes." (PMID 37627015, 2023). "Results indicated high expression of IL4I1, TDO2, NIT2, and IDO1, while IDO2, ADI1, DDC, HPD, BHMT2 exhibited low expression in most cancers." (PMID 38691253, 2024).
bacterial infection (1 paper, 2017). "It has been shown that NIT1 as well as NIT2 expression is induced in the course of bacterial infection with Plasmodiophora brassicae." (PMID 28174581, 2017).
NIT2 also shares sentences with these, for which no sentence is quoted: folate deficiency (1 paper); thyroid cancer (1).